TNF (tumor necrosis factor)
Diseases named in the same sentence as TNF in open-access papers (continued):
Sharing a sentence is not in itself a finding about the gene and the disease.
atherosclerosis (continued). "The top 10 COPD-related pathways were associated with cancer, PI3K-Akt signaling, fluid shear stress and atherosclerosis, MAPL signaling, Fc epsilon RI signaling, longevity regulation, chemokine signaling, NF-κB signaling, TNF signaling, and T cell receptor signaling." (PMID 36290608, 2022). "Nevertheless, it remains to be shown whether anti-TNFα treatment may reduce vascular ceramide production and attenuate CVD and atherosclerosis." (PMID 36233252, 2022). "The results show that XFZYD might regulate fluid shear stress and atherosclerosis, AGE-RAGE signaling pathway, TNF signaling pathway, and IL-17 signaling pathway to influence the development of AS." (PMID 35960089, 2022). "Tumor necrosis factor-alpha (TNF-α) is a proinflammatory cytokine that plays a crucial role in host defense and mediates the pathogenesis of several disease processes, including atherosclerosis, septic shock, and autoimmune disease." (PMID 36614858, 2022). "Th1 cells secrete pro-inflammatory factors such as IFN-γ and tumor necrosis factor alpha (TNF-α), which initiate or promote atherosclerosis inflammatory responses and increase plaque instability by activating monocyte-macrophages and DCs and affecting Treg stability." (PMID 36703734, 2022). "Thus, TNFα seems to be a key player in several shared pathologic mechanisms of both FGR and atherosclerosis." (PMID 36294369, 2022). "Moreover, the lipid and atherosclerosis, PI3K-Akt signaling pathway, IL-17signaling pathway, TNF signaling pathway, proteoglycans in cancer were enriched." (PMID 36545317, 2022). "Studies showed that in vitro treatment of miR-146a may induce the expression of proinflammatory factors such as TNF-α, NF-κB p65, and MCP-1, which are essential transcription factors in atherosclerosis." (PMID 39281713, 2022). "Also, the genes that are involved with the inflammatory responses like VCAM1, MCP1, M-CSF, IL-1β, TNF α and β, IL-6, M-CSF, MCP-1, IL-18 and CD-40L, etc. were thoroughly studied to elucidate their role in atherosclerosis." (PMID 35241081, 2022). "• In an in vitro study, oleuropein at the dose of 20 μg/ml showed anti-inflammatory activity after 30 min of administration by inhibiting the secretion of tumor necrosis factor alpha (TNF-α)–induced matrix metalloproteinase 9 (MMP-9), which additionally resulted in the anti-atherosclerosis effect." (PMID 35496299, 2022). "Moreover, TP decreased the secretion of ox-LDL-induced tumor necrosis factor alpha (TNF-α), interleukin 1 beta (IL-1β), and monocyte chemotactic protein-1 (MCP-1), an important profoam cell cytokine in atherosclerosis." (PMID 36387364, 2022). "Results show that HQJZD was mainly involved in signaling pathways of atherosclerosis, AGE-RAGE, T-cell receptors, TNF-α, IL-17, toll-like receptors, hepatitis C, pancreatic cancer, colorectal cancer, bladder cancer, toxoplasmosis, and others, in treating H. pylori gastritis." (PMID 36249768, 2022). "However, a recent study on atherosclerosis reported a strong relation between CCL4, IL-6, and tumor necrosis factor α (TNF-α)." (PMID 36290379, 2022). "Thus, several inflammatory mediators such as high C-reactive protein (CRP) and circulating pro-inflammatory markers such as tumor necrosis factor-α (TNF-α) and interleukins are involved in the pathogenesis of IBD, as well as in atherosclerosis." (PMID 35892915, 2022). "Moreover, new data has shown that TNF-α increases the transcytosis of LDL-chol across human endothelial cells and contributes to early atherosclerosis by enhancing subendothelial retention of LDL-chol in the vascular walls." (PMID 35163364, 2022). "Moreover, it is well established that RA related pro-inflammatory cytokines, tumor necrosis factor alpha (TNF-α), interleukin-1b (IL-1b) and IL-6, have a pivotal role in atherosclerosis and metabolic dysregulation." (PMID 35207457, 2022).
atherosclerosis (continued). "The serum levels of TC, TG, LDL-c, TNF-α, hs-CRP, NO, and MDA in the HWT group with atherosclerosis were significantly increased, while the HDL-c levels were decreased markedly and were substantially different from those in the WT and miR-351−/− groups (P < 0.05)." (PMID 36180828, 2022). "Moreover, miR-146a increases proinflammatory factor (TNF-α, MCP-1, and NF-κB p65) expression, which plays a vital role in atherosclerosis and ASC progression." (PMID 39281713, 2022). "Inflammatory cells begin to gather, infiltrate, and release inflammatory factors, such as Interleukin-1 (IL-1), Interleukin-6 (IL-6), and tumor necrosis factor-α (TNF-α), which play a pivotal role in the injury-induced inflammatory response and the atherosclerosis." (PMID 36139086, 2022). "TNFα could induce IL6 and IL1β as a cellular signaling molecule attributing to the inflammatory regulation in atherosclerosis, or act as a pro-inflammatory molecule to promote hypertension or atherosclerosis with IL6 and IL1β." (PMID 33318871, 2021). "The finding that pro-inflammatory cytokines such as interleukin (IL)-1β and tumor necrosis factor-α (TNF-α) could give rise to the expression of adhesion molecules and chemokines by ECs providing a support of the inflammatory basis of atherosclerosis." (PMID 35008500, 2021). "Atherosclerosis can also induce an inflammatory response through oxidized low-density lipoprotein (LDL) particles that stimulate the synthesis of cytokines, interleukin 6 (IL-6), tumor necrosis factor α (TNF-α), interferon and nuclear factor κB." (PMID 34441451, 2021). "In a study involving over 200 patients with psoriatic arthritis, half receiving traditional disease-modifying antirheumatic drugs (DMARDs) and half receiving a TNF-α blocker, patient carotid intima-media thickness (C-IMT) was measured as an indicator of subclinical atherosclerosis." (PMID 33668632, 2021). "As atherosclerosis progresses, inflammatory cells and macrophages phagocytosing Ox-LDL increase and produce tumor necrosis factor-α (TNF-α), interleukin-8 (IL-8), interleukin-1 (IL-1), and other important inflammatory factors that further aggravate atherosclerosis." (PMID 34015766, 2021). "The KEGG enrichment result indicated that the genes were associated with AGE-RAGE signaling pathway (hsa04933), fluid shear stress and atherosclerosis (hsa05418), PI3K-Akt signaling pathway (hsa04151), TNF signaling pathway (hsa04668), and NF-kappa B signaling pathway (hsa04064)." (PMID 34594388, 2021). "TNF-α is a proinflammatory agent with a distinct mechanism of action compared with other inflammatory mediators, which reinforces the relevance of clinical investigation addressing TNF-α regulation in atherosclerosis." (PMID 34199767, 2021). "Different anti-TNF-α therapies have been studied in patients with documented atherosclerosis, although the clinical results were not entirely consistent and further insights are warranted regarding the regulation of TNF-α in patients with SCAD." (PMID 34199767, 2021). "Under high glucose conditions, vascular endothelial cells produce high levels of proinflammatory cytokines, such as TNF-α and IL-1β, ROS (reactive oxygen species) and high levels of VCAM-1 and E-selectin, which initiate atherosclerosis via adhesion of circulating leukocytes to the endothelium." (PMID 34445477, 2021). "The importance of immune cell-derived TNF-α is further demonstrated by an elegant experiment, showing that bone marrow transplantation from animals lacking TNF-α is able to reduce atherosclerosis development in ApoE KO mice." (PMID 33770265, 2021). "It has been shown that TNF-mediated inflammation in endothelial cells directs the formation of RELA- and BRD4-dependent SEs, being BET inhibition able to abrogate SEs-derived transcription and atherosclerosis." (PMID 34439792, 2021).
atherosclerosis (continued). "The enrichment analysis indicated that the KEGG pathway mainly focuses on AGE-RAGE signaling pathway in diabetic complications, Relaxin signaling pathway, TNF signaling pathway, PI3K-Akt signaling pathway, fluid shear stress, and atherosclerosis signaling pathways." (PMID 34273999, 2021). "For KEGG analysis, the most significant pathways are all associated with oxidative stress, namely, pathways in cancer, lipid and atherosclerosis, and fluid shear stress and atherosclerosis; AGE-RAGE pathway; TNF pathway; IL-17 pathway; and microbial infection-related pathways." (PMID 34970312, 2021). "Indeed, there is growing evidence that proinflammatory cytokines, such as IL-1, IL-6, TNF-α and CRP, contribute to atherosclerosis and adverse cardiovascular outcomes and predict mortality in ESRD patients." (PMID 32770957, 2020). "Taking into account our results, we hypothesized that the high level of plasma lipids, increased the secretion of IL-6, IFN-γ and TNF-α, subsequently activating JAK2/STAT3 to induce and aggravate atherosclerosis." (PMID 32169038, 2020). "In this study, the direct inhibition of CCL4 could decrease circulating IL-6 and TNF-α levels, suggesting the potential modulation of downstream inflammatory cytokines by blocking CCL4 in atherosclerosis in vivo." (PMID 32911750, 2020). "CD47−/− can trigger T cell activation, but the activation of T cells will not promote atherosclerosis because T cell activation in CD47−/− mice does not produce more TNF-α compared with the wild type." (PMID 32733941, 2020). "The results showed that rabbits with atherosclerosis presented higher IL-6, IL-1β, IFN-γ and TNF-α levels than those in the control group; however, ruxolitinib substantially decreased IL-6, IL-1β, IFN-γ and TNF-α contents in rabbits with atherosclerosis." (PMID 32169038, 2020). "Additionally, increasing IL-10, IL-4, IL-13, and TGF-β and reducing IL-1β, Il-6, TNF-α, CCL3, CCL4, and CCL5 can slow the progression of atherosclerosis." (PMID 32346605, 2020). "CoQ10 could also inhibit the inflammatory proteins such as IL-6, TNF-α, ICAM-1, VCAM-1 and NLRP3, thus exerting the role inhibiting atherosclerosis." (PMID 32792941, 2020). "TNF-α has a central role in controlling inflammatory processes and atherosclerosis development independent of plasma cholesterol levels." (PMID 33014098, 2020). "Similarly, Decitabine treatment downregulated the expression of inflammation genes, TNF-α, IL-6, and IL-1β, and the chemotaxis gene MCP-1 resulting in the amelioration of atherosclerosis." (PMID 32714333, 2020). "LECT2 mitigated the expression and secretion of IL-1β, IL-8, TNF-α, and IL-1β dose-dependently in Apoe–/– mice fed with a Western diet, suggesting that LECT2 may inhibit atherosclerosis by alleviating inflammatory responses via Wnt/β-catenin signaling." (PMID 31310065, 2019). "Various studies have shown that anti-TNF drugs act on the symptoms and signs of RA, and therefore on atherosclerosis – as is shown by albeit nonsignificant improvement in the carotid alteration and arterial stiffness of our patients." (PMID 31285841, 2019). "Therefore, we exposed TNFα-treated HUVECs to Irisin and BAIBA because TNFα is involved in atherosclerosis progression." (PMID 30858489, 2019). "The inability of CLO to prevent TNFα from inducing TF, together with the higher serum TNFα levels seen in CLO treatment, may have led to greater atherosclerosis in CLO-treated mice than in TIC-treated mice in the current study." (PMID 31242230, 2019). "In the Atherosclerosis + Knockdown group, serum levels of TNF-α and IL-1β significantly decreased (P < 0.01), whereas the serum level of TGF-β1 significantly increased (P < 0.01), as compared with the Atherosclerosis + Vector group." (PMID 31781638, 2019).
atherosclerosis (continued). "Activation of FXR pathways in mouse models of atherosclerosis could almost completely inhibit aortic atherosclerotic lesion formation, attenuated the pro-inflammatory expression of IL1ß, IL6 and TNF and negatively modulated NFκB-mediated inflammation." (PMID 31191690, 2019). "TRAF6 is located in the cytoplasm and interacts with cell surface receptors like CD40 (a marker of the proinflammatory M1 macrophage phenotype), which is a member of the tumor necrosis factor (TNF) receptor family and plays a role in the progression of atherosclerosis." (PMID 31766552, 2019). "Our results verified that TNF-α administration substantially increased the levels of inflammatory cytokines, such as interleukins, MCP-1, MMP-2, and MMP-9, that mainly contribute to the development of vessel dysfunction in atherosclerosis." (PMID 30577658, 2018). "In conclusion, the present study found an interaction between the TNF-α 1031T/C polymorphism and HTLV-I for the risk of atherosclerosis-related disease incidence, but not for the risk of total death and cancer incidence." (PMID 28576445, 2017). "When activated, endothelial cells release inflammatory mediators like interleukin-1, tumor necrosis factor-α, etc. and induce adhesion molecules like JAM-A and ZO-1, resulting in endothelial dysfunction and increased vascular permeability, particularly atherosclerosis and cardiovascular diseases." (PMID 28854981, 2017). "Previous reports have demonstrated that TNFα or IL-1β knockout mice show an alleviation of atherosclerosis, without an improvement in serum lipid parameters." (PMID 28777298, 2017). "Most importantly, oxidative stress, endogenous molecules (TNF-α, PDGF, and interleukin), and apoptosis inducer are responsible for EMPs release to undergo functional change in blood vessel eventually leading to the pathology of atherosclerosis." (PMID 27066292, 2016). "Furthermore, the role of TNF-α, IFN-γ, IL-1β, IL-6, IL-8, IL-4 and IL-10 in the pathogenesis of atherosclerosis in carotid artery post-carotid endarterectomy has been documented." (PMID 27271180, 2016). "To determine whether exacerbated atherosclerosis with Ad-C5a treatment was correlated with increased inflammatory cytokines expression, we analyzed the plasma level of IL-6, IFN-γ and TNF-α in mice." (PMID 27517153, 2016). "Given the important roles of the CD40/CD40L axis in the inflammatory response and ROS production in oxidative stress during the pathological process of atherosclerosis, we explored the mechanisms by which resveratrol reduces CD40 expression and ROS generation induced by TNF-α." (PMID 26799794, 2016). "Polarization towards the proinflammatory phenotype can be induced in vitro by toll-like receptor (TLR) ligands, including TNFα, lipopolysaccharide (LPS), and interferon γ (IFN-γ) that might also play a role in the pathogenesis of atherosclerosis." (PMID 26885534, 2016). "To further reveal the mechanisms of reducing atherosclerosis lesions by blocking TLR4/NF-κB, we investigated the effects of Ad-TLR4 siRNA and NF-κB antagonist PDTC on inflammatory cytokines such IL-1β, MCP-1, and TNF-α." (PMID 25860573, 2015). "Increased plasma concentrations of TNF-α, IL-6, FFA, and PAI-1 and decreased concentrations of adiponectin may lead to accelerated atherosclerosis, plaque instability, and arterial thrombosis." (PMID 25935836, 2015). "Studies of atherosclerosis have shown that OxLDLs are recognized by macrophage pattern-recognition receptors (PRRs) such as CD36 and TLR-4 and promote proinflammatory signaling, such as TNF-α and leukocyte recruitment." (PMID 25922566, 2015). "Atherosclerosis, precursor to cardiovascular diseases, is recognised as a chronic inflammatory disease of large arteries, involving cytokines, such as IFN-γ and TNF-α, adhesion molecules, such as ICAM-1 and VCAM-1, and several plasma inflammatory markers, such as hsCRP, IL-6, and fibrinogen." (PMID 26346892, 2015).
atherosclerosis (continued). "Based on the effects of IL-6 and TNF-α in inflammatory reaction and atherosclerosis, the role of CCC in preventing atherosclerosis may be related to inhibiting the inflammation reaction." (PMID 26539229, 2015). "TNF-α and IFN-γ are crucially involved in the progression of atherosclerosis." (PMID 25830298, 2015). "TNF alpha is an additional surrogate marker relating IBD and early atherosclerosis." (PMID 25699123, 2015). "Meanwhile, the expressions of IL-6, TNF-α, MCP-1 and VCAM-1 were up-regulated in apoE-/- mice treated with salusin-β, indicating that salusin-β could aggravate the progression of atherosclerosis via up-regulation of inflammatory molecules." (PMID 24621517, 2014). "IL-1β, TNF-α, MCP-1 and MMP-2 can promote the progression of atherosclerosis." (PMID 24755612, 2014). "To date, there is evidence that patients with OSA have increased TNF-α values; differently, the correlation between this cytokine and a marker of early atherosclerosis, such as cIMT, has still not been evaluated among OSA subjects." (PMID 24481114, 2014). "Our results showed many abnormalities of crucial functions and pathways in the pathogenesis of atherosclerosis, for instance, increased inflammation, platelet activation, and functional inhibition of VEC as well as pathway of TGF-β, JAK-STAT, PI3K/AKT and TNF-α." (PMID 25333956, 2014). "In addition, some studies have shown a correlation between subclinical atherosclerosis and selected proinflammatory factors such as C-reactive protein (CRP), fibrinogen, tumor necrosis factor-α (TNF-α), and interleukin-6 (IL-6)." (PMID 24772446, 2014). "Our findings here are thus consistent with TNF-α and LDL could initiate the process of atherosclerosis and correlated to the phenotypic changes of our present model." (PMID 24010774, 2013). "Neutralization of IL-17A not only reduced the atherosclerotic plaques but also down regulated IL-6, TNF-α and CCL5 that suggests that regulation of these cytokines may be interconnected in atherosclerosis." (PMID 23437105, 2013). "Finally, p38α is critical for the production of multiple pro-inflammatory cytokines like tumor necrosis factor (TNF) and interleukins IL-1β, IL-6 and IL-8 in most of the cell types that participate in atherosclerosis development." (PMID 21695272, 2011). "In our study, postprandial plasma CRP, but not haptoglobin, IL-6 or TNF-α, positively correlated with the severity of beginning atherosclerosis." (PMID 21756316, 2011). "Since the amount of MIP-2 alpha, a cytokine rather not related to atherosclerosis, is not affected by PON1 polymorphism, the observed changes of TNF-alpha and MCP-1 levels observed in the current study are most likely specific." (PMID 21569287, 2011). "Atherosclerosis involves growth factors, cytokines and vaso-regulatory factors such as vascular endothelial growth factor (VEGF), fibroblast growth factor (FGH), transforming growth factor-β (TGF-β), interleukin-1 (IL-1) and tumor necrosis factor -α (TNF-α)." (PMID 21867503, 2011). "IL-1β, IL-6 and TNF-α trigger atherogenesis by sensitizing vascular smooth muscle cells and inducing secretion of cellular adhesion molecules and matrix metalloproteinase (MMP) by monocytes during later stages of atherosclerosis." (PMID 20543948, 2010). "Tumor necrosis factor (TNF) receptor-associated factors (TRAFs) are intracellular adaptor proteins, which channel signaling for members of the TNF-/interleukin-1 (IL-1)-/toll-like-receptor (TLR)-superfamily such as TNFα, CD40L, and IL-1β, proteins known to promote inflammation and atherosclerosis." (PMID 20644648, 2010). "Exogenous IFN-γ has been shown to enhance high fat diet induced atherogenesis in ApoE-/- mice and IFN-γ and TNF-α knockout mice did not develop severe atherosclerosis when fed with a diet with high cholesterol." (PMID 19604372, 2009).